CCL2 (C-C motif chemokine ligand 2)
Diseases named in the same sentence as CCL2 in open-access papers (continued):
Sharing a sentence is not in itself a finding about the gene and the disease.
tumor (continued). "It was reported that trabectedin has dual effects on anticancer including inducing the differentiation and apoptosis of malignant cells and regulating the tumor microenvironment by limiting the associated inflammatory mediator production such as CCL2, interleukin-6, and VEGF." (PMID 36438821, 2022). "In addition, CCL2 plays a role in the recruitment of tumor-associated macrophages, which promote tumor phenotype generation as well as tumor cell invasion and angiogenesis." (PMID 35770088, 2022). "In the same way, CCL2 produced by tumor cells and CSF1 produced by tumor-associated fibroblasts contribute to the generation of M2-like macrophages, and CXCL1 production by tumor cells has been linked to increased myeloid cell populations and decreased tumor infiltration of cytotoxic CD8+ T cells." (PMID 36408139, 2022). "GNB4 expression was notably related to the tumor-associated macrophage (TAM) markers CCL2 (Cor = 0.527, P = 1.64e−28), IL10 (Cor = 0.61, P = 5.02e−40), M2 macrophage marker CD163 (Cor = 0.66, P = 1.01e−48), VSIG4 (Cor = 0.64, P = 5.17e−45), and MS4A4A (Cor = 0.723, P = 1.26e−62)." (PMID 35756485, 2022). "CIN is strongly associated with CCL2 expression in the tumor microenvironment." (PMID 36188003, 2022). "Indeed, MDSCs and TAMs emit IL10 and TGF-β, while tumor-associated neutrophils (TANs), TAMs, and CAFs secrete CCL2 attracting and expanding the population of Tregs inside the tumor." (PMID 35392957, 2022). "CCL2 overexpression is associated with poor patient prognosis in various tumor types." (PMID 35740975, 2022). "With the adjustment based on purity, the correlation analysis in STAD revealed that DDR1 was closely linked to most of immune markers in various TIICs, such as CD3E of general T cells, CD86 of monocytes, CCL2 of tumor-associated macrophages (TAMs), and CCR7 of neutrophils." (PMID 35935941, 2022). "In several studies, CCL2 was also associated with tumor cell migration and metastasis." (PMID 35562953, 2022). "Similarly, CCL1 and CCL2 have been shown to promote tumour metastasis by facilitating tumour‐associated macrophage recruitment." (PMID 36068649, 2022). "Tumor-associated neutrophils (TANs) secrete CCL2 to facilitate the progression of cancer." (PMID 36077785, 2022). "CCL2 also attracts different immune cells to form an immunosuppressive microenvironment, which promotes the formation of tumor‐associated microvasculature and supports the growth and metastasis of tumor cells." (PMID 35702353, 2022). "Importantly, CCL2 has been implicated as one of the main cytokines involved in tumor cell re-establishment in the bone marrow in PCa." (PMID 35406450, 2022). "Indeed, use of anti-CCL2 antibodies have been associated with reduced macrophage infiltration and tumor growth." (PMID 33924237, 2021). "Pearson correlation coefficients were calculated, and the results indicated that BGN presented the strongest correlations with TIIC markers for monocytes (CD86, CD115), tumor-associated macrophages (TAMs) (IL-10, CCL2, CD68), M2 macrophages (CD163, VSIG4, and MS4A4A) and Tregs (FOXP3, CCR8, TGFβ)." (PMID 35096572, 2021). "CCL2 has been shown to be expressed in tumor-associated macrophages." (PMID 33467469, 2021). "Furthermore, loss of a classical tumor-suppressor gene PTEN induces expression of CCL2 and VEGF, thereby blocking T-cell infiltration and promoting resistance to the ICIs." (PMID 33436555, 2021). "Furthermore, in fibrosarcoma (MCA) and mammary (PyMT) murine tumor models, the CCR2/CCL2 axis participates in the recruitment of Tregs from the lymph node to the tumor, as Ccr2-deficient Tregs were unable to infiltrate the TME." (PMID 33924428, 2021). "Corroborating our observation of CCL2′s association with tumor progression, the limited reports on MCPs in CRC have indicated, albeit not unanimously, an increase in CCL2 expression along with an advancing clinical stage, which has been accompanied by the accumulation of TAMs." (PMID 34885960, 2021).
tumor (continued). "Therefore, to eliminate the pro-metastatic effect of orthotopic tumor proliferation induced by CCL2, a novel mouse model was developed to overexpress CCL2 only in the lung via adeno-associated virus (AAV) inhalation." (PMID 34249913, 2021). "In addition, LNMAT1-induced CCL2 regulated the tumor microenvironment in BCa tissues through tumor-associated macrophages (TAMs) infiltration and VEGF-C upregulation, which ultimately led to lymphangiogenesis and lymphatic metastasis." (PMID 33869048, 2021). "The CCR2/CCL2 axis also plays a particularly important role in attracting monocytes, which, after interactions with tumor- and stromal-derived factors, differentiate into suppressive tumor-associated macrophages at the site." (PMID 34646829, 2021). "In the TME, tumor-associated macrophages (TAMs) comprise the majority of the population within the cellular milieu and are usually activated by a variety of chemokines, from chemokine C-C motif ligand 2 (CCL2) to CCL5." (PMID 33805919, 2021). "After adjusting for tumor purity, the results showed that ATF3 expression was significantly correlated with macrophage subpopulations, including tumor-associated macrophages (TAMs; CCL2, r = 0.245, P = 4.16e−06), M1 (NOS2, r = 0.137, P = 0.08e−02), and M2 (CD163, r = 0.141, P = 8.90e−03)." (PMID 33407456, 2021). "Moreover, PTEN loss can increase tumor cell resistance to T-cell killing by significantly upregulating CCL2 and VEGF." (PMID 33746989, 2021). "CCL2 secreted from cancer-associated mesothelial cells could promote the malignant potential of OC, playing a crucial role in the tumor microenvironment of OC." (PMID 34638514, 2021). "In addition, CCR2-deficient MDSCs and the deletion of CCL2 reduced the recruitment of MDSCs into tumor sites of murine tumor models." (PMID 34441758, 2021). "WTI-induced alterations within lung tissues in combination with (Ccl2-mediated) vascular dysfunction, particularly increased vascular permeability, were shown to increase the risk of circulating tumor cell extravasation followed by metastatic seeding into irradiated lungs tissues." (PMID 34209135, 2021). "Exosomes secreted by primary tumor cells could generate a pre-metastatic niche by regulating cytokine expression, we herein evaluated the association of BC-derived exosomes and CCL2." (PMID 34249913, 2021). "Tumor recruits macrophages and “educates” them to become tumor-associated-macrophages (TAMs), which behave like MDSCs; MDSCs are chemotactically attracted by CCL2." (PMID 34061898, 2021). "In this study, we found that EE could reduce serum CCL2, downregulate the expression of CCL2 in tumor cells and tumor-associated immune cells, and increase the number of CD8+ T cells by suppressing TAMs and G-MDSCs infiltration." (PMID 34593796, 2021). "Evidence suggests that CCL2 is released from tumor cells and promotes phenotypic changes in sensory neurons, which might explain how tumor cells drive functional changes in nociceptors to cause hyperalgesia." (PMID 34575835, 2021). "Chemokine CCL2 could induce the recruitment of M2-like tumor-associated macrophages and regulatory T cells, thereby coordinating the initiation of metastasis with immunosuppression and neovascularization." (PMID 34177903, 2021). "Moreover, CCL2 hindered the activation of docetaxel‐induced apoptosis‐associated protein caspase‐3 to support tumour cell growth." (PMID 34464477, 2021). "Additionally, CCL2 has been found to recruit tumor associated macrophages, which are known to confer resistance to anti-VEGF therapies by participating in vascular sprouting." (PMID 34931665, 2021). "Tumor-associated nerves promote PNI because of CCL2 chemotactic actions." (PMID 32555170, 2020).
tumor (continued). "Zhou L et al57 discover for the first time to our knowledge that, neddylation inactivation exhibits its anti‐tumor activity by suppressing the recruitment of monocytes/tumor‐associated macrophages in the tumor microenvironment, in response to Cullin‐1/NF‐κB‐modulated CCL2 derived from tumor cells." (PMID 32749072, 2020). "Next, we were interested in determining whether there were differences in prognosis between the two tumor stage groups (pT2 vs. pT3+4) that were associated with CCL2 staining in IC in the Kaplan–Meier analysis." (PMID 32429318, 2020). "In addition to causing a drop in free CCL2 levels and a reduction in the level of tumor-infiltrating macrophages, this therapy resulted in a temporary antitumor activity." (PMID 32175278, 2020). "Furthermore, CCL2 positivity in TC was associated with a 2.10-fold increased risk of tumor-associated death (p = 0.050) for patients with adjuvant chemotherapy." (PMID 32429318, 2020). "Tumor-associated macrophages (TAMs) mainly originate from BM precursors, recruited into cancer tissue by chemokines (e.g., CCL2, CCL5, and CXCL12), growth factors (e.g., CSF1) and products of the complement cascade, although local proliferation has been demonstrated in some tumors." (PMID 32650452, 2020). "Moreover, CCL2 inhibits maturation of monocytes to macrophages causing more accumulation of senescent cells and contributing to tumor immune escape." (PMID 32570952, 2020). "In the tumor microenvironment, macrophages are infiltrated (they are called ‘tumor-associated macrophages’) and activated, expressing CSF-1 and CCL2, which may promote intravasation and metastasis." (PMID 30496442, 2019). "CTRP1 expression was associated with the tumor-infiltrating macrophages and CCL2 in GBM." (PMID 31183364, 2019). "Moreover, the HOX transcript antisense intergenic RNA (HOTAIR) was also associated with tumor growth and angiogenesis, as well as for the CCL2-mediated recruitment of MDSCs and TIMs (namely, TAMs)." (PMID 31847487, 2019). "For example, in murine breast cancer, a rebound effect has been noted after the withdrawal of anti-CCL2 treatment, which has been associated with increased mobilization and infiltration of bone-marrow monocytes in the tumor and consequent acceleration of lung metastasis." (PMID 31878087, 2019). "Through its CCR2 receptor affinity, it activates downstream signaling pathways, such as p42/44 MAPK, phospholipase C-γ, and protein kinase C. Elevated levels of CCL2 protein and mRNA expression are implicated in cancer, showing a high tumor grade and poor prognosis." (PMID 31665136, 2019). "Ex vivo experiments with tumor associated macrophages showed that SW could partially modulate macrophage phenotype, decreasing CCL2 secretion and impairing IL-10 and IL-6 upregulation, which prompted us to proceed to in vivo tests." (PMID 30840689, 2019). "Given that chemokines can enter cells via their functionally‐active receptors, we hypothesized that fluorescently‐labelled CCL2 analogues would allow us to detect CCR2+ metastasis‐associated macrophages in tumours." (PMID 31535788, 2019). "Furthermore, we find that administration of a CCR2 antagonist or the loss of CCL2 expression in tumor cells enhances the antitumor activity of PD-1 blockade, providing a salvage alternative for residual tumors after iRFA." (PMID 31780645, 2019). "Moreover, abundant clinicopathological data have verified the association between high concentrations of CCL2 in tumor with increased TAM infiltration and metastatic events." (PMID 31300030, 2019).
tumor (continued). "In addition, CAF secretion of CXCL1, CXCL2, CXCL5, CXCL6, CXCL8, and CCL2 recruits tumor-associated neutrophils (TANs) to the TME and polarizes them to an N2 pro-tumoral phenotype." (PMID 31058816, 2019). "Moreover, targeting CCL2 decreased the recruitment of both tumor-associated macrophages (TAMs) and myeloid-derived suppressor cells (MDSCs) to the tumor site and reduced primary tumor growth." (PMID 30059519, 2018). "CCL2 is produced by tumor cells and the associated stromal cells." (PMID 29361917, 2018). "Despite CCL2 being implicated as a prominent contributor in tumor progression, the molecular mechanisms of CCL2 induction still remain largely unknown." (PMID 29934505, 2018). "Most results are related to the evidence that CCL2 overexpression in tumour is associated with macrophage infiltration and poor prognosis in human cancers and may play a pivotal role in creating the fertile environment in the bone for metastasis." (PMID 29682101, 2018). "FBW7 depletion in BM-derived stromal cells (BMSCs) results in the accumulation of Notch-1 intracellular domain (NICD1) and increased secretion of CCL2, which in turn promotes recruitment of monocytic myeloid-derived suppressor cells (Mo-MDSCs) and tumor-associated macrophages (TAMs)." (PMID 30053872, 2018). "Importantly, higher CCL2 scores as determined by immunohistochemistry were more frequently seen in brain metastatic tissue than in matched primary tumor tissue and additionally CCL2 expression correlated with PTEN loss in brain metastatic tissue." (PMID 29312881, 2017). "Tumor-associated macrophages (TAMs) may differentiate from peripheral blood monocytes recruited in a MCP-1/CCL2-dependent manner (hereafter CCL2)." (PMID 26625205, 2016). "In line with this hypothesis, recent data from clinical trials showed that inhibiting CCL2 by targeting its receptor or by inhibiting its expression effectively reduced tumor-associated macrophages." (PMID 26684239, 2016). "Collectively, these gain‐ and loss‐of‐function studies suggested that CCL2 might be involved in tumor growth, angiogenesis, and macrophage infiltration in ccRCC." (PMID 27666332, 2016). "In addition to promoting recruitment of macrophages to the primary tumor site, CCL2 has also been implicated in indirectly promoting the seeding and growth of tumor cells in the metastatic site." (PMID 26884646, 2016). "IL-17A could promote the ESCC tumor cells to produce more chemokines CCL2, CCL20 and CXCL13, which were associated with the migration of B cells." (PMID 26942702, 2016). "We show here that targeting serpinE2 via KD or by treatment with the antibody causes a reduction in the population of tumor-promoting macrophages, as well as a decrease in chemokine ligand 2 (CCL2), which is known to stimulate macrophage abundance and polarization." (PMID 27793045, 2016). "In fact, CCL2 has been implicated in various neoplasias and adopted as a therapeutic target." (PMID 27191744, 2016). "In addition to CSF-1 and CCL2, other chemokines have also been linked to macrophage recruitment in the primary tumor site." (PMID 26884646, 2016). "CCL2 can directly promote angiogenesis through the recruitment of tumor-associated macrophages." (PMID 26528477, 2015). "Monocytes are a major source of CCL2, but CCL2 is also produced by a variety of cells in tumors, including epithelial tumor cells and the cellular components of the tumor microenvironment, such as endothelium, stroma and tumor-associated macrophages (TAMs)." (PMID 26327448, 2015). "Similarly, CCL2 is a potent macrophage chemoattractant and is associated with macrophages and tumor stages." (PMID 25588753, 2015). "Downregulation of the Ccl2 and Ccl5 genes associated with this pathway may preclude efficient recruitment of various immune effectors into tumors or tumor-bearing tissue." (PMID 26441959, 2015).
tumor (continued). "The attenuation of CCL2 production caused by clodronate liposome exposure suggested that monocyte recruitment might also play a role in tumor progression." (PMID 25505466, 2014). "The tumor microenvironment may favor tumor growth inhibition because of down-regulation of tumor-associated chronic inflammatory mediators, in particular CCL2, and reduced MDSC recruitment." (PMID 24980831, 2014). "Tumor-associated macrophages (TAMs) are derived mostly from circulating monocytes which are attracted into tumor sites by locally produced chemotactic factors, such as CCL2, CCL5, CCL7, CCL8, and CXCL12, and macrophage colony stimulating factor (M-CSF)." (PMID 24966464, 2014). "CCL2 is a chemokine that has been implicated in assisting cancer metastasis by mediating a crosstalk between cancer cells and the stromal cells that are present in the tumor microenvironment." (PMID 25054153, 2014). "Some studies have implicated that CCL2 was an active participant in the tumor microenvironment." (PMID 23697837, 2013). "This paradoxical observation suggests that although the broader gefitinib response signature may confer protective effects, CCL2 specifically could drive tumor-associated macrophage (TAMs) recruitment, potentially counteracting therapeutic efficacy by remodeling the tumor microenvironment." (PMID 40808689, 2025). "Alterations in FOS expression have been associated with malignant phenotypic changes in tumor cells, while downregulation of CCL2 and CAV1 may influence immune cell recruitment and signaling within the tumor microenvironment, thereby affecting tumor immune evasion and progression." (PMID 41155558, 2025). "Within the complex tumor microenvironment, multiple cellular constituents - including malignant cells, adipocytes, cancer-associated fibroblasts, and tumor-associated macrophages - contribute to CCL2 production through both paracrine and autocrine signaling mechanisms." (PMID 41276817, 2025). "While the mechanism of lurbinectedin is still being explored in the tumor and tumor microenvironment, preclinical models indicate that lurbinectedin reduces tumor-associated macrophages (TAMs) and reduces the production of certain inflammation and growth factors, including CCL2 and VEGF." (PMID 37999116, 2023). "In addition, HMGA2, a tumour derivative, could up‐regulate the gene transcription of CCL2 in tumour‐associated macrophages (TAMs) by regulating the STAT3 signalling pathway." (PMID 36872292, 2023). "Furthermore, secretion of CCL2 (mainly by tumor-associated astrocytes) in the BTME of MB was reported as responsible for leptomeningeal metastasis, thus also promoting the recruitment of other immune cells, including those derived from the bone marrow-derived macrophages." (PMID 36968588, 2023). "Given that CCR4 deficiency does not affect the infiltration and migration of monocytes, CCR4 inhibition to block the CCL2/CCR4 axis could be a promising novel antitumoral strategy to reduce the risk of rapid tumor recurrence and metastasis during the cessation of CCL2 inhibition treatment." (PMID 35177591, 2022). "As a well-known molecule, CCL2 could recruit M2 macrophages to promote tumor progression, and its reduction means that the tumor immune microenvironment was predisposed to anti-tumor." (PMID 36013004, 2022). "In this study, we hypothesized that the HMC3 cells, upon stimulation with anti-inflammatory cytokines (IL-4, IL-13, IL-10, TGFβ, CCL2) released from cancer cells, will show an increased expression of immuno-suppressive and tumor-supportive proteins and associated pathways." (PMID 34566949, 2021). "Significant decreases in the expression of cytokines are associated with tumor-associated macrophages (TAMs), including IL-4, IL-10 CCL-2, CCL-22, and CXCl-12, and suggest that the reduction in macrophages within the treated tumors could be indicative of a decrease in TAMs." (PMID 33956631, 2021).